INS (insulin)
Diseases named in the same sentence as INS in open-access papers (continued):
Sharing a sentence is not in itself a finding about the gene and the disease.
type 2 diabetes (continued). "Our observation of higher rates of hypoglycemia in younger type 2 diabetes patients can be explained by the higher insulin sensitivity in this group." (PMID 28913365, 2017). "In fact, the heterogeneous character of type 2 diabetes results from the dynamic interaction between defects in insulin secretion and insulin action." (PMID 29211033, 2017). "Regular physical activity is an effective therapeutic approach for the treatment of insulin sensitivity and type 2 diabetes." (PMID 28469249, 2017). "Due to the strong links between mTOR signalling and insulin signalling, many efforts have been made to create mathematical models of the two combined especially in the area of Type 2 diabetes mellitus (T2DM)." (PMID 28096317, 2017). "In many situations, insulin is the preferred agent in type 2 diabetes where there is active TB infection." (PMID 29270319, 2017). "Median fasting and 2 h post-load plasma concentrations of glucose and insulin, and HbA1c increased in the order NGM to prediabetes to type 2 diabetes, whereas median insulin sensitivity decreased with impairment of glucose metabolism." (PMID 27933333, 2017). "The prevalence of celiac disease among patients with type 2 diabetes, with poor glycemic control despite insulin therapy, is slightly higher than the actual CD prevalence in general population." (PMID 28985731, 2017). "Patients with IR and type 2 diabetes mellitus (T2DM) show defects in insulin-stimulated glucose metabolism in skeletal muscle." (PMID 28367451, 2017). "Cheaper alternatives to insulin therapy such as metformin can be used in the management of type II diabetes and GDM." (PMID 28828389, 2017). "The effect of α-GIs to decrease blood glucose and insulin levels and prevent the development of type 2 diabetes in patients with impaired glucose tolerance is well established." (PMID 28805670, 2017). "In a Chinese study, a higher incidence of abnormal glucose metabolism, insulin secretion and type 2 Diabetes had been identified, when 16 GS patients were compared with healthy individuals." (PMID 28446151, 2017). "Our results suggest that LMF and Fx supplementation exerts a beneficial effect on hepatic glucose levels and glucose homeostasis possibly because of the improvement in insulin sensitivity in type II diabetes db/db mice." (PMID 28387741, 2017). "In this study, the mechanisms controlling IRS2-dependent insulin signaling were analyzed using the db/db mouse model of type 2 diabetes and the MIN6 mouse insulinoma cell line." (PMID 28886131, 2017). "BCF indices reflecting early-phase insulin secretion have the best ability to discriminate individuals who will develop prediabetes and type 2 diabetes." (PMID 27933333, 2017). "While subjects with type 2 diabetes were more insulin resistant than healthy controls at baseline, nicotine infusion significantly decreased insulin sensitivity in type 2 diabetics but did not modify the insulin response in controls." (PMID 27699443, 2017). "Type 2 diabetes (T2DM) is due to the limited ability of the body to respond to the action of insulin." (PMID 29096704, 2017). "Since elevated GH blocks insulin action, individuals with acromegaly are prone to hyperglycemia, insulin resistance and type 2 diabetes." (PMID 28933734, 2017). "The thiazolidinedione (TZD) groups of antidiabetic drugs, such as troglitazone are used in the cure of type II diabetes to reduce blood glucose levels and improve the sensitivity of numerous tissues to insulin." (PMID 28460464, 2017). "Understanding the molecular networks controlling ectopic lipid deposition and insulin responsiveness in skeletal muscle is essential for developing new strategies to treat type 2 diabetes." (PMID 27981357, 2017).
type 2 diabetes (continued). "Meanwhile, type II diabetes mellitus has been associated with an increased risk of neurodegenerative disease, such as Alzheimer’s disease and Parkinson’s disease, and studies have shown that metabolic dysfunction and abnormalities surrounding insulin signaling may underlie disease progression." (PMID 28649604, 2017). "Glipizide is a second-generation oral hypoglycemic medicine for the cure of type II diabetes because of its capability to selectively stimulate insulin secretion from β-cells." (PMID 29245957, 2017). "Given the insulin resistance of pregnancy, it is likely that most women with type 2 diabetes before pregnancy will require treatment with insulin during their pregnancy, simply to maintain glycaemic control." (PMID 28770325, 2017). "ARB-mediated type 2 diabetes protection is supported by cell line experiments in which the AGTR1 blocker increased insulin secretion and proinsulin synthesis." (PMID 29192236, 2017). "The role of adiponectin in influencing insulin sensitivity and body fat contents is a matter of extensive research in the field of complex metabolic diseases such as obesity and type 2 diabetes." (PMID 28445413, 2017). "Failure to secrete sufficient quantities of insulin is a pathological feature of type-1 and type-2 diabetes, and also reduces the success of islet cell transplantation." (PMID 28887564, 2017). "Our aim was to investigate the prevalence of celiac disease among insulin-using type 2 diabetes patients with inappropriate glycemic control." (PMID 28985731, 2017). "The prevalence of QTc interval prolongation is relatively high in type 2 diabetes patients, possibly due to reduced insulin sensitivity." (PMID 28912840, 2017). "It has also been reported recently that HDAC7 expression is increased in the pancreatic islets of type 2 diabetic patients and the expression of Tcf7l2 is promoted independently of histone acetylation to suppress insulin secretion." (PMID 28886131, 2017). "To try and fill the gaps in knowledge, we conducted this study to analyze the frequency and potential predictors of self-monitored hypoglycemia in type 1 and insulin-treated type 2 diabetes in an ambulatory setting." (PMID 28913365, 2017). "In this trial, we aimed to verify the superiority of dapagliflozin to therapy with DPP-4 inhibitors and insulin in type 2 diabetes patients for MAGE." (PMID 28725273, 2017). "In type 2 diabetes, decreased levels of insulin promote an increase in both PDK4 gene expression and PDK2 mRNA levels." (PMID 28298922, 2017). "In total, 304 insulin- and liraglutide-naïve patients with type 2 diabetes were enrolled in this observational study; they received liraglutide therapy for 12 weeks." (PMID 28074109, 2017). "We conducted a retrospective observational study to examine the impact of insulin treatment on the muscle mass of patients with type 2 diabetes." (PMID 28246927, 2017). "The oral insulin-sensitizing drug metformin is a first line therapeutic in the management of Type 2 diabetes (DM2), and has also been shown to have antiproliferative activity in vitro against multiple cancer cells lines." (PMID 29211738, 2017). "Adiponectin exerts beneficial effects in type 2 diabetic patients since it is related to increased insulin sensitivity in a variety of tissues." (PMID 28878683, 2017). "Near normalisation of blood glucose levels has been shown to restore the insulin-secretory effect of GIP in both animal models of type 2 diabetes and in humans with this condition, providing evidence that defective GIP receptor signalling is reversible." (PMID 28004148, 2017). "Type 2 diabetes, found in >90% of all cases of diabetes, is characterized by insulin resistance and a defective secretion of insulin." (PMID 29042645, 2017). "Several previous studies consistently showed that caffeine consumption induced an acute reduction in insulin sensitivity among individuals who were healthy, obese, or had type 2 diabetes." (PMID 28054966, 2017).
type 2 diabetes (continued). "More than 90% of patients however display a type-2 diabetes phenotype (T2D), which is characterized in a first step by impaired insulin action in peripheral tissues, and initially high compensating endogenous levels of insulin." (PMID 28575111, 2017). "Thiazolidinediones (TZDs), the peroxisome proliferator-activated receptor γ (PPARγ) agonists, are one of the insulin-sensitive drugs that have been used for the treatment of type 2 diabetes." (PMID 29362600, 2017). "Both are necessary conditions for the development of type 2 diabetes since a normal response of pancreatic β-cells usually compensates for insulin resistance and maintains normal blood glucose level." (PMID 28606124, 2017). "In patients with type 2 diabetes previously on insulin and treated with BIL, large VLDL concentration increased from baseline." (PMID 28587667, 2017). "GNB3-T/+ mice have elevated fasting plasma glucose, insulin, and C-peptide, as well as glucose intolerance, indicating type 2 diabetes." (PMID 29206867, 2017). "In 390 insulin-treated individuals with type 2 diabetes studied over 4.3 years, there was a striking 40% reduction in cardiovascular events, a pre-specified secondary outcome, in those randomised to metformin." (PMID 28770327, 2017). "This post hoc analysis confirms and expands previous knowledge about outcomes of basal insulin initiation in type 2 diabetes insufficiently controlled on oral glucose-lowering drugs." (PMID 28151905, 2017). "Six of the patients had type 2 diabetes treated with metformin (n = 5), liraglutide (n = 2), pioglitazone (n = 1) and insulin (n = 3)." (PMID 28392935, 2017). "This study focused upon skeletal muscle cells as skeletal muscle is the predominant site of insulin-mediated glucose uptake and skeletal muscle insulin resistance is considered to be the primary defect in type 2 diabetes." (PMID 28053672, 2017). "Yet, although such intervention initiate the reversal of type 2 diabetes, the trajectory toward real cure (i.e., restoration of organ insulin sensitivity and beta-cell insulin excretion) will take much more effort and time." (PMID 29403436, 2017). "A number of animal models of insulin-independent type 2 diabetes and insulin-dependent diabetes exist, but their application in comparative biomedical research depends on the context of the disease being studied." (PMID 28093504, 2017). "Type 2 diabetes (T2D) is a metabolic dysfunction characterized by hyperglycemia resulting from insulin resistant and β-cell dysfunction." (PMID 28166749, 2017). "This experimental induction of increased insulin demand along with a reduction in functional β-cell mass is designed to mimic crucial manifestations in the pathogenesis of human type 2 diabetes, which can be accomplished within a condensed time frame." (PMID 28093504, 2017). "Our data provide proof of concept for future experiments testing the potential of intranasal application of insulin to ameliorate defective homeostatic control in patients with type 2 diabetes." (PMID 29042645, 2017). "Insulin therapy is essential in both type 1 diabetes and late-stage type 2 diabetes, with current therapeutic insulins being designed to restore the normal biphasic insulin response to food intake." (PMID 29222417, 2017). "The ratio of circulating PI:insulin is also increased in obesity and is predictive of the development of IR and type 2 diabetes." (PMID 28466412, 2017). "Emerging evidence indicates that gut microbiota-host interactions play a key role in the pathophysiology of type 2 diabetes and modulates energy homeostasis, glucose homeostasis and insulin resistance." (PMID 28765642, 2017). "In Phase 2/3 studies of basal insulin peglispro (BIL) compared to insulin glargine, patients with type 1 or type 2 diabetes previously treated with insulin and randomized to BIL had an increase in serum triglycerides (TGs)." (PMID 28587667, 2017).
type 2 diabetes (continued). "Almost all of the remaining type 2 diabetic patients either received oral hypoglycemic reagents such as sulfonylurea, or glinides which stimulate insulin secretion from pancreatic beta cells." (PMID 28811505, 2017). "Large prospective population studies show that higher BMI is associated with adverse blood lipid levels, higher fasting glucose and insulin, type 2 diabetes mellitus and CHD." (PMID 28889241, 2017). "Such training has been demonstrated to result in greater insulin sensitivity and better overall blood glucose levels, at least in adults with type 2 diabetes." (PMID 28265261, 2017). "We used these metabolites and the clinical covariates of sex, age, BMI, family history and fasting insulin measured in the DESIR study samples to predict the progression of these individuals to type 2 diabetes." (PMID 28597074, 2017). "Type 2 diabetes (T2D) is manifested by progressive metabolic impairments in tissues such as skeletal muscle and liver, and these tissues become less responsive to insulin, leading to hyperglycemia." (PMID 28067838, 2017). "It is known that East Asian type 2 diabetes is characterized by generally lesser obesity and higher insulin sensitivity compared with Caucasians." (PMID 28086872, 2017). "Type 2 diabetes occurs when the body is unable to produce sufficient insulin or is unable to process insulin properly." (PMID 28952561, 2017). "Protein tyrosine phosphatase 1B (PTP1B) has been recognized as a major negative regulator of insulin signaling and therefore has been identified as a possible drug target for the treatment of type 2 diabetes and obesity." (PMID 28491237, 2017). "It plays a key role in the signaling cascade of insulin and therefore is a key target in the treatment of type 2 diabetes." (PMID 28635658, 2017). "In at-baseline non-diabetic individuals, disposition indices ΔI30/ΔG30, ΔCP30/ΔG30 and corrected insulin response at 30 min had ROC AUCs of over 80% for incident type 2 diabetes." (PMID 27933333, 2017). "Unless corrected, metabolic complications can increase the risk of developing type II diabetes mellitus (T2DM), predominantly characterized by loss in insulin sensitivity (insulin resistance), and is a disease strongly associated with NAFLD." (PMID 29270905, 2017). "This highlighted the importance of some treatment strategies, such as avoiding drugs that overstimulate beta cells and initiating insulin therapy at an appropriate time to preserve endogenous beta cell activity in the progression of type 2 diabetes." (PMID 28228847, 2017). "PPAR gamma agonists thiazolidinediones (TZDs) improve insulin sensitivity in peripheral tissues and ameliorate glucose tolerance and insulin sensitivity in type 2 diabetic patients." (PMID 28620312, 2017). "This improves glycemic control in patients with type 2 diabetes, primarily by suppressing glucagon levels and increasing endogenous insulin secretion." (PMID 29340105, 2017). "Type 2 diabetes is characterised by reduced metabolic sensitivity to insulin and insufficient insulin secretion by pancreatic beta cells." (PMID 27933333, 2017). "Therefore, the functional identity of the beta cell is indissolubly linked to its capacity to secrete insulin in response to increased glucose levels, which is regulated by several intracellular organelles and mechanisms and whose impairment is the hallmark of type 2 diabetes." (PMID 28589121, 2017). "GlycA predicted for impaired insulin secretion, incident type 2 diabetes, and CVD events and adverse changes in glycemia during the follow-up period." (PMID 28911155, 2017). "Combinations of insulin sensitizers and insulin secretagogues like glucagon-like peptide-1 receptor agonist have been used for treating type 2 diabetes even in Caucasians." (PMID 29104217, 2017).
type 2 diabetes (continued). "TZDs quickly passed clinical trials and became front-line agents in the treatment of type II diabetes for their robust insulin-sensitizing and glucose-lowering actions, although their popularity has recently decreased in response to safety concerns." (PMID 28123453, 2017). "The UKPDS revealed a 15% reduction in myocardial infarction and a 13% reduction in death among people with new-onset type 2 diabetes treated intensively with antidiabetic agents and insulin, as needed to attain an HbA1c of 7.0% vs. usual care." (PMID 28725272, 2017). "Instead they found an increase in AMPKα1 mRNA and decrease in AMPKα2 mRNA levels which was correlated to the transition from insulin resistance to type 2 diabetes development." (PMID 28628674, 2017). "In people with type 2 diabetes, the proportion treated with sulfonylureas had declined from 36.8 to 22.4% (p < 0.001), while insulin-treatment had increased from 11.7 to 18.7% (p < 0.001)." (PMID 28824815, 2017). "All aspects of beta cell function, including first- and second-phase insulin responses, were significantly increased in participants with type 2 diabetes treated with semaglutide vs placebo after 12 weeks of treatment." (PMID 28526920, 2017). "In obese patients with type 2 diabetes, rosiglitazone increased insulin sensitization through upregulation of mRNA levels of PPARδ and PGC-1α, as well as stimulation of SDH activity in skeletal muscles." (PMID 29201040, 2017). "In this sense, a positive effect of leucine and phenylalanine on insulin secretion was reported in a clinical assessment of type II diabetes patients and controls, which showed in a 3-fold increase in secretion compared with carbohydrate alone." (PMID 28793331, 2017). "In the same context, pharmacological activation of AMPK increases glucose uptake in skeletal muscles of subjects with type 2 diabetes by an insulin-independent mechanism." (PMID 29422987, 2017). "Insulin secretion in islets taken from patients with type 2 diabetes is reported to be reduced by 50% after normalization for islet insulin content." (PMID 28742858, 2017). "Previous studies have also demonstrated that GAG significantly ameliorates hyperglycemia, increases blood insulin level, and improves the glucose tolerance in animals with type 2 diabetes." (PMID 28947964, 2017). "It account for approximately 80% of glucose absorption under insulin-stimulated conditions and a reduction in insulin-stimulated glucose uptake in skeletal muscles of type 2 diabetic patients has been observed both in vitro and in vivo." (PMID 28642704, 2017). "Hypoglycemia is common in type 1 diabetes, and its occurrence increases with insulin use in type 2 diabetes." (PMID 28913365, 2017). "The main purpose of the present study was to validate the Italian version of the DEPS-R scale, extending validation to a representative sample of insulin-treated male and female subjects with type 1 and type 2 diabetes aged from 13 to 55 years." (PMID 28724422, 2017). "] are randomized controlled trials that used human insulin and the insulin analogue glargine, respectively, in type 2 diabetes and evaluated long-term cardiovascular outcomes." (PMID 28725272, 2017). "The rates of severe hypoglycemia in insulin-treated type 2 diabetes are reported to be low, but these have been recorded in the context of clinical trials and often in people with a short duration of insulin therapy." (PMID 28913365, 2017). "Clocks, operative in the pancreatic islets, have caught particular attention in the last years due to recent reports on their critical roles in regulation of insulin secretion and etiology of type 2 diabetes." (PMID 28439257, 2017). "Considering the fact that these tax levies are imposed on the sick and are inequitable, and most diabetic patients are children (Type 1 Diabetes) and elderly (Type 2 diabetes), there is a strong rationale to exempt insulin from VAT." (PMID 28836974, 2017).